PLPPR1 (phospholipid phosphatase related 1)
Description:
May play a role in neurite outgrowth and neurogenesis.
Synonyms: PRG-3; LPPR1; MGC26189; FLJ20300
Tractability: Antibody: UniProt places it where antibodies can reach, with medium confidence; UniProt predicts a signal peptide or a membrane-spanning region; its Gene Ontology location is reachable by antibodies, with medium confidence. PROTAC: its protein half-life has been measured.
Gene: Protein-coding gene on chromosome 9 (101,028,727 to 101,325,135, forward strand). Ensembl gene ENSG00000148123.
Subcellular location: Cell membrane; Cell projection, neuron projection
Subcellular location (Human Protein Atlas): Nucleoplasm
Pathways (Reactome):
Signal Transduction: Lysosphingolipid and LPA receptors
Gene Ontology:
Molecular function: protein binding; lysophosphatidic acid phosphatase activity
Biological process: nervous system development; phospholipid dephosphorylation; phospholipid metabolic process; signal transduction
Cellular component: nucleoplasm; neuron projection; plasma membrane
Genetic constraint (gnomAD): Loss-of-function variants: 9 observed, 29.18 expected, observed/expected ratio (o/e) 0.31, 90% interval 0.19 to 0.54. The upper end of that interval is the gene's LOEUF score, 0.54, which puts it in group 2 of 6, group 1 being the genes least tolerant of losing a copy. Missense variants: 258 observed, 375.78 expected, observed/expected ratio (o/e) 0.69, 90% interval 0.62 to 0.76. Synonymous variants: 132 observed, 143.64 expected, observed/expected ratio (o/e) 0.92, 90% interval 0.8 to 1.06.
Homologues: Orthologues: chimpanzee PLPPR1 (100% identical), macaque PLPPR1 (99% identical), guinea pig PLPPR1 (97% identical), rabbit PLPPR1 (97% identical), pig PLPPR1 (97% identical), mouse Plppr1 (96% identical), rat Plppr1 (96% identical), dog PLPPR1 (94% identical), tropical clawed frog plppr1 (82% identical), zebrafish plppr1 (65% identical), Drosophila melanogaster CG11437 (22% identical), Caenorhabditis elegans plpp-1.1 (21% identical), and 7 more. Paralogues in human: PLPPR5 (54% identical), PLPPR2 (48% identical), PLPPR4 (38% identical), PLPPR3 (38% identical), PLPP1 (25% identical), PLPP3 (24% identical), PLPP2 (21% identical), PLPP5 (16% identical), PLPP4 (16% identical).
Diseases named in the same sentence as PLPPR1 in open-access papers:
PLPPR1 is named in the same sentence as 15 diseases in open-access papers, as found by Europe PMC text mining. Sharing a sentence is not in itself a finding about the gene and the disease. The quoted sentences say what the papers report.
breast carcinoma (2 papers, 2018 to 2022). "PLPPR1 has been shown to be downregulated in breast cancer and in glioblastoma tissue; in the latter, both up- and downregulated PLPPR1 levels are associated with shorter survival of glioblastoma patients." (PMID 36187351, 2022).
hepatocellular carcinoma (1 paper, 2025). A malignant tumor that arises from hepatocytes. "In conclusion, this study identified and internally evaluated a five-gene metabolic signature (PLPPR1, CNTN3, HOXA10, HAGLR, and ENPP3) associated with immunotherapy response in hepatocellular carcinoma through integrative analysis of multiple transcriptomic datasets." (PMID 41515582, 2025).
neuroblastoma (1 paper, 2022). Neuroblastoma (NB) is the most common solid, extracranial childhood tumor. "Overexpression of PLPPR1 in hippocampal neurons counteracts the inhibitory effects of CSPGs and myelin on neurite outgrowth and a similar effect is observed in neuroblastoma cells and LPA-induced neurite retraction." (PMID 36187351, 2022). "PLPPR1 overexpression in neuroblastoma cells increases the number and length of neurites, while PLPPR3 expression in stem-cell derived motor neurons led to a PI3K-dependent formation of multiple axons per cell." (PMID 36187351, 2022). "Furthermore, super resolution microscopy of co-overexpressed PLPPR1 and PLPPR5 or PLPPR3 showed both puncta formation at the plasma membrane in neuroblastoma cell lines." (PMID 36187351, 2022).
tumor (2 papers, 2024 to 2025). "PLPPR1 encodes a membrane-associated phospholipid phosphatase–related protein involved in lipid signaling and membrane dynamics, processes increasingly recognized as critical for immune receptor signaling, immune cell activation, and metabolic fitness within the tumor microenvironment." (PMID 41515582, 2025).
cancer (1 paper, 2022). A tumor composed of atypical neoplastic, often pleomorphic cells that invade other tissues. "Knockdown of PLPPR1 leads to a reduction in the number of filopodia in cancer cell lines, as well as in hippocampal neurons." (PMID 36187351, 2022). "In another transcriptome study, PLPPR1, PLPPR3 and PLPPR5 are among the top 25 most differentially expressed membrane proteins in pediatric cancer types." (PMID 36187351, 2022).
kidney disease (1 paper, 2022). "Although PLPPR1 and SFXN1 genes have not been reported to be associated with kidney disease, the current study found that PLPPR1 and SFXN1 were significantly positively correlated with QDPR and negatively correlated with HAS2 and MYOF." (PMID 35320116, 2022).
PLPPR1 also shares sentences with these, for which no sentence is quoted: Ewing sarcoma (1 paper); fibrosarcoma (1); glioblastoma (1); glioma (1); papillary thyroid carcinoma (1); Parkinson disease (1); primitive neuroectodermal tumor (1); Stroke (1); urinary tract infection (1).